GSK3B (glycogen synthase kinase 3 beta)
Diseases named in the same sentence as GSK3B in open-access papers (continued):
Sharing a sentence is not in itself a finding about the gene and the disease.
Alzheimer disease (continued). "Therapeutic use of PI3K/Akt inhibitors has been applied in patients with differenttypes of cancer, whereas GSK3β protein inhibitors are used in the treatment ofneurodegenerative diseases such as Alzheimer’s disease." (PMID 32130369, 2020). "GSK-3β or tau-kinase I is particularly abundant in the central nervous system (CNS), playing a key role in the pathogenesis of Alzheimer’s disease (AD)." (PMID 33013321, 2020). "Previous studies haveshown clearly that inhibiting GSK3B has proven therapeutic significance in Alzheimer's disease, but its contribution to various cancers hasnot been clearly resolved." (PMID 31354196, 2019). "Glycogen synthase kinase-3β (GSK-3β) represents a relevant drug target for the treatment of neurodegenerative pathologies including Alzheimer’s disease." (PMID 31242571, 2019). "β-Sitosterol prevented oxidative stress and lipid peroxidation in neuronal cells via ERα/PI3K/GSK3β signaling, suggesting the chemical is effective against Alzheimer’s disease." (PMID 31234352, 2019). "β-Sitosterol activates ERα/PI3K/GSK3β signaling to increase resistance to oxidative stress, which is beneficial for the treatment of neurodegenerative diseases, such as Alzheimer’s disease." (PMID 31234352, 2019). "There is one serine/threonine protein kinase downstream of Akt, GSK-3β, which is known to play important roles in many disorders such as oxidative stress, cancer, diabetes, psychiatric disorders, and Alzheimer's disease." (PMID 31011401, 2019). "Consistent with this, GSK-3β inhibition has been shown to reduce Aβ production in Alzheimer’s disease murine models, and to lessen Aβ-induced neurotoxicity in cultured neurons." (PMID 30987146, 2019). "Hyperglycemia accelerates the progression of Alzheimer’s disease (AD), and GSK3β plays a potential link between AD and hyperglycemia." (PMID 30426182, 2019). "Inhibition of glycogen synthase kinase 3β (GSK-3β) is considered to be the central therapeutic approach against Alzheimer’s disease (AD)." (PMID 30413117, 2018). "In fact, despite increased PP1 activity, tau remains hyperphosphorylated in Alzheimer’s disease suggesting that elevated tau phosphatase activity of PP1C cannot counterbalance increased GSK3β activity." (PMID 29631601, 2018). "Recent studies have identified GSK-3β as a potential therapeutic target in Alzheimer ́s disease, bipolar disorder, stroke, more than 15 types of cancer, and diabetes." (PMID 29561817, 2018). "In this study, using a molecular docking method to screen a virtual library, we discovered molecules that can simultaneously inhibit Glycogen synthase kinase-3 beta and cyclin-dependent kinase 5 as lead compounds for the treatment of Alzheimer's disease." (PMID 28179579, 2017). "We next studied the same issue in a model with GSK-3β overexpression in the forebrain (Tet/GSK-3β mice) that was previously demonstrated to display an Alzheimer’s disease-like phenotype." (PMID 27832289, 2017). "On the other hand, Co-IP results showed that Drp1 binds directly to GSK-3β in N2a cells, in line with previous results in an Alzheimer's disease study." (PMID 28591721, 2017). "7-bromoindirubin-3-oxime (7Bio), an indirubin derivative derived from indirubin-3-oxime, possesses inhibitory effects against cyclin-dependent kinase-5 (CDK5) and glycogen synthase kinase-3β (GSK3β), two pharmacological targets of Alzheimer's disease (AD)." (PMID 29234273, 2017). "In Alzheimer’s disease, GSK3β increases Drp1-dependent GTPase activity and results in modified neurons being more vulnerable to apoptotic signals; in contrast, blocking GSK3β-induced Drp1 phosphorylation efficiently protects neurons against apoptosis." (PMID 28098754, 2017). "CDKs and GSK3β are also targets for many neurodegenerative disorders, such as Alzheimer's disease (AD) and Parkinson's disease (PD)." (PMID 29234273, 2017).
Alzheimer disease (continued). "Despite this growing body of preclinical data supporting a role for GSK3β in diabetes, most clinical trials using GSK3β inhibitors study neurological diseases such as Alzheimer's Disease and Progressive Supranuclear Palsy." (PMID 27534430, 2016). "A recent study found that TubA can activate Akt by enhancing Akt phosphorylation at Ser473 and inhibit GSK-3β by increasing phosphorylation of GSK-3β at Ser9 in the brains of Alzheimer’s disease mice." (PMID 26790818, 2016). "In some neurological disorders, such as Alzheimer's disease, the protein level of GSK3β has been shown to be elevated in the brain, suggesting that such mechanism also has an important role in other neurological processes." (PMID 26313916, 2015). "Alzheimer disease’s patients exhibit high levels of circulating GSK3β and, consequently, pharmacological strategies based on GSK3β antagonists have been designed." (PMID 25764078, 2015). "Recently GSK3β inhibitors have been described as promising drugs for several pathologies such as diabetes, stroke, mood disorders, inflammation, and Alzheimer’s disease." (PMID 26056602, 2015). "Dysregulation of GSK3β expression leads to many pathological conditions, including neuronal dysfunction, Alzheimer’s disease, and Parkinson’s disease." (PMID 25644719, 2015). "Toxic Aβ that promotes GSK3β activity bridges a link between the two hallmarks of Alzheimer's disease, implicating that GSK3β inhibitor is a potential drug target." (PMID 25136630, 2014). "In resting cells, GSK3β is constitutively active, and its over-activation is presumably involved in numerous brain diseases, such as Alzheimer’s disease." (PMID 23658842, 2013). "GSK-3β and β-catenin are regulated either directly or indirectly by lithium, valproate, antidepressants, and antipsychotics, while GSK-3β has also been identified as a target for the treatment of Alzheimer's disease." (PMID 23862076, 2013). "Accordingly, dysregulation of GSK3β activity in the brain is involved in many neurological diseases and psychiatric disorders, such as Alzheimer’s disease, schizophrenia and bipolar disorder." (PMID 23658842, 2013). "Neurobiological focus on GSK3β stems from its demonstrated functions in neuronal differentiation and in cognition, and from its role as “tau-kinase I” in Alzheimer’s disease (AD)." (PMID 23705847, 2013). "Human Tau protein forms filaments in the brains of patients with Alzheimer disease, and glycogen synthase kinase-3β (GSK-3β) phosphorylation plays an important role in Alzheimer disease." (PMID 22558423, 2012). "In the recent decade small molecule inhibitors of GSK-3β are emerging as a promising drug for treatments against neurodegenerative diseases, radiation damage, Alzheimer's disease, diabetes, and cancer." (PMID 22675363, 2012). "GSK-3β inhibitors are currently being utilized for the treatment of various diseases including Alzheimer's disease and other neurodegenerative diseases, diabetes, inflammatory disorders, radiation damage, and cancer." (PMID 22675363, 2012). "Secondary to the role of GSK-3β in various diseases including Alzheimer's disease, inflammation, diabetes, and cancer, small molecule inhibitors of GSK-3β are gaining significant attention." (PMID 22675363, 2012). "Glycogen synthase kinase 3 (GSK3α and GSK3β) are serine/threonine kinases involved in numerous cellular processes and diverse diseases including mood disorders, Alzheimer’s disease, diabetes, and cancer." (PMID 22792253, 2012). "There are numerous studies showing that abnormal increases in the level and activity of GSK-3β induce neuronal cell death paired helical filament tau formation, and neurite retraction in Alzheimer's disease (AD)." (PMID 21603026, 2011). "The present study not only supports the importance of GSK3 kinases (including GSK3α and GSK3β) as critical nodes in the progression of Alzheimer's disease, but also emphasizes the central role of GSK3 in regulating intracellular trafficking." (PMID 20520769, 2010).
Alzheimer disease (continued). "Activation of GSK-3β is presumed to be involved in various neurodegenerative diseases, including Alzheimer's disease (AD), which is characterized by memory disturbances during early stages of the disease." (PMID 18958152, 2008). "It demonstrated that cerebrosides could attenuate excessive tau protein phosphorylation by modulating the PI3K/Akt/GSK-3β signaling pathway, thereby exhibiting significant neuroprotective potential in the context of Alzheimer’s disease." (PMID 40137277, 2025). "This study focused on the abnormal phosphorylation of tau and its aggregation process, characteristic of Alzheimer’s disease, and aimed to compare the morphology and formation process of phosphorylated tau aggregates produced by four kinases: Cdk5/p25, GSK3β, MARK4, and p38α." (PMID 41155414, 2025). "Moreover, tideglusib, another GSK3β inhibitor, has been investigated for its potential in treating conditions such as Alzheimer’s disease and cancer." (PMID 41190025, 2025). "In Alzheimer’s disease and tauopathies, aberrant activation of GSK-3β drives pathological tau hyperphosphorylation and neurofibrillary tangle formation, while phosphorylation by AKT at Ser9 acts upstream to inhibit GSK-3β, thereby promoting neuronal protection and synaptic stability." (PMID 41455863, 2025). "The diseases of GSK-3β activated by LPS are oral cancer, esophageal cancer and Alzheimer’s disease." (PMID 40843171, 2025). "GSK3β is a key regulator of autophagy, especially in Alzheimer’s disease." (PMID 41190025, 2025). "In various sterile inflammatory models such as collagen-induced arthritis, ischemia-reperfusion injury, streptozotocin-induced diabetes, and Alzheimer’s disease, GSK3β activation was induced and administration of GSK3β inhibitors effectively reduced inflammatory response." (PMID 39923112, 2025). "In Alzheimer’s disease, the mechanisms of lithium action may also involve the GSK-3β inhibition, lithium’s effect on mitochondria, and its anti-herpes activity." (PMID 40283904, 2025). "This study investigated the regulatory role of the long non-coding RNA maternally expressed gene 3 (MEG3) in tau hyperphosphorylation and insulin signaling (PI3K/AKT1/GSK3β) under high-glucose (HG)-induced neurotoxic conditions mimicking Alzheimer’s disease pathology." (PMID 40869265, 2025). "Furthermore, Cer attenuated Aβ1-42-induced tau hyperphosphorylation by activating the PI3K/Akt/GSK3β signaling pathway in male SD rats as an Alzheimer’s disease model." (PMID 40863627, 2025). "Furthermore, the neuroprotective mechanism of the compounds against Alzheimer’s disease revealed that suppressing the phosphorylation of tau protein by the PI3K/Akt/GSK3β pathway leads to improved synaptic plasticity and reduced nerve fiber tangles." (PMID 40863627, 2025). "Interestingly, in Alzheimer’s disease, acetylation of GSK3β at residue K15 (the equivalent of TgGSK K13) leads to the over-activation of the kinase, leading to the hyperphosphorylation of tau." (PMID 40152591, 2025). "The experimental investigation of the V317F mutant GSK-3β's effect on neurodegeneration may enhance the understanding of the biomarker potential of rs140668532 in Alzheimer's disease." (PMID 40520520, 2025). "GSK3β expression is increased in human Alzheimer’s disease and colocalizes with NFTs." (PMID 40349043, 2025). "In Alzheimer’s disease, especially, GSK3β has been shown to phosphorylate the protein tau33,34." (PMID 37163077, 2024). "In addition to the direct role of ATRA on tau tangle formation, it can also indirectly inhibit tau hyperphosphorylation in Alzheimer’s disease by the RARA/glycogen synthase kinase 3 beta (GSK-3β) pathway." (PMID 38572181, 2024). "GSK‐3β kinase dysregulation aggregates Aβ production and accumulation in Alzheimer's disease (AD)." (PMID 39129397, 2024). "GSK‐3β inhibitors with their therapeutic application in Alzheimer's disease." (PMID 39129397, 2024).
Alzheimer disease (continued). "GSK3β is a kinase involved in cellular death and in the development of Alzheimer’s disease." (PMID 39595827, 2024). "Clinical investigation of GSK‐3β inhibitors as the future therapy of Alzheimer's disease." (PMID 39129397, 2024). "Experimental study showed that TPPU could alleviate spatial learning and memory deficits in Aβ‐induced Alzheimer's disease mice through the regulation of glycogen synthase kinase 3β (GSK3β)‐mediated NF‐κB and Nrf2 signaling pathways." (PMID 38156378, 2023). "Since obesity is closely related to T2DM, and Alzheimer’s disease (AD) is also recognized as “type III diabetes,” we checked the expression of genes encoding proteins that are involved in amyloid-beta (Aβ) generation (ADAM10, BACE1, PSEN2, and GSK3β)." (PMID 37432552, 2023). "GSK3β is the primary kinase that causes hyper-phosphorylation of tau species in mouse models of Alzheimer’s disease, because the overexpression of GSK3β in mouse hippocampal neurons increases hyper-phosphorylated tau and causes neuronal death and memory impairment." (PMID 37754222, 2023). "In addition, elevated GSK-3β activity is also associated with Alzheimer’s disease and there is a direct link with hyperphosphorylation of DRP2 at GSK-3β-dependent phosphorylation sites and increased amyloid precursor protein." (PMID 37175950, 2023). "These novel designed molecules may be taken as lead potential GSK-3β inhibitors towards the treatment of Alzheimer’s disease." (PMID 37893156, 2023). "Curcumin-primed exosomes could prevent the neuronal death to relieve the symptoms of Alzheimer's disease by inhibiting phosphorylation of the Tau protein through activating the AKT/GSK-3β pathway." (PMID 37605121, 2023). "And blockage of GSK3β-regulated Drp1 phosphorylation could provide neuroprotection in neuronal and mouse models of Alzheimer's disease." (PMID 38102662, 2023). "The results of pathological examination of the brain in Alzheimer’s disease suggest that two proteins, cyclin-dependent kinase 5 (Cdk5) and GSK3β, may be involved in the hyper-phosphorylation of tau." (PMID 37754222, 2023). "In addition, studies using IHC showed that GSK3β and phosphorylated tau are co-localized in the hippocampal neurons in Alzheimer’s disease." (PMID 37754222, 2023). "Based on pathological examinations of the brain in Alzheimer’s disease, two proteins, cyclin-dependent kinase 5 (Cdk5) and glycogen synthase kinase 3β (GSK3β), may be involved in the abnormal phosphorylation of tau." (PMID 37754222, 2023). "This review provides a comprehensive overview of the intricate mechanisms of this enzyme and evaluates the existing evidence regarding the therapeutic potential of GSK-3β in brain diseases, including Alzheimer’s disease, Parkinson’s disease, mood disorders, and glioblastoma." (PMID 38107562, 2023). "It has also been demonstrated that inhibition of GSK3β can reduce the accumulation of Aβ in the body to a certain extent and can alleviate the reduction of spatial learning and memory in transgenic animals with Alzheimer’s disease." (PMID 37645701, 2023). "Therefore, inhibition of GSK-3β is regarded as a prospective therapeutic strategy for central nervous system (CNS)-related disorders, especially Alzheimer’s disease (AD) (Eldar-Finkelman & Martinez, 2011; Lauretti, Dincer & Praticò, 2020)." (PMID 38107562, 2023). "A pivotal protein that connects Wnt signaling and Alzheimer’s disease is GSK3β." (PMID 36292931, 2022). "It was reported that overexpression of GSK-3β promotes abnormal hyperphosphorylation of tau protein, exacerbates neuronal degeneration, disrupts normal synaptic plasticity, and accelerates the pathological process in Alzheimer's disease patients." (PMID 35781592, 2022).
Alzheimer disease (continued). "The mean Manders M2 coefficient was calculated for each subject, and Student’s t-test showed a trend (T = −2.18, P = 0.07) towards increased overlap of GSK3β signal with nuclear staining in Control versus Alzheimer’s disease, providing likely validation of the mass spectrometry results." (PMID 35611312, 2022). "In the present work, we examine whether meridianins are capable to inhibit neural GSK3β in vivo and if such inhibition induces improvements in the 5xFAD mouse model of Alzheimer’s Disease." (PMID 35281935, 2022). "In rodents with Alzheimer’s disease, caffeic acid improved cognitive skills and redox status and decreased the formation of beta-amyloid plaques; the mechanism of these changes correlated with decreased GSK3β levels." (PMID 36614030, 2022). "We also focus on GSK3β and DYRK1A, markers of Alzheimer’s disease, which are also closely associated with pancreatic β-cell dysfunction and type 2 diabetes, and thus may represent common therapeutic targets for both diseases." (PMID 36499613, 2022). "The NLRP3, BACE1, AChE, and GSK-3β are closely related to Alzheimer’s disease." (PMID 35991454, 2022). "A previous study has demonstrated that Sulforaphene (SF), one of the main isothiocyanates isolated from a Chinese herb Raphani Semen, holds the ability of activating PI3K/AKT signaling pathway to enhance p-GSK-3β deposition, thereafter exerting neuroprotective effects in Alzheimer's disease (AD)." (PMID 35186189, 2022). "Consequently, it has been suggested that GSK3β plays a fundamental role in the progression of neuroinflammatory disorders, such as Alzheimer’s disease and multiple sclerosis." (PMID 36613781, 2022). "β isoform of GSK-3 is accountable for neurofibrillary tangle formation and Tau hyperphosphorylation, so molecules showing GSK-3β antagonistic property could be an optimistic approach for the treatment of Alzheimer’s disease." (PMID 36590911, 2022). "In addition, all-trans-retinoic acid (RA) induction would enhance the neuronal morphological differentiation of SH-SY5Y cells and augment Alzheimer's disease markers such as tau and GSK3-β expression." (PMID 33820886, 2021). "Interestingly, stimulation of the PI3K/Akt pathway can also activate GSK3β, which, in contrast, mediates neuronal death in Alzheimer’s disease and Parkinson’s disease." (PMID 34830487, 2021). "Due to the actions GSK-3 has over the expression of Nrf2 target genes, current research has led to the development of novel multitargeted therapeutics that both inhibit GSK-3β and induce Nrf2 for the treatment of inflammatory diseases, such as Parkinson’s and Alzheimer’s disease." (PMID 34571919, 2021). "Therefore, GSK3-β misregulation would increase total tau protein through hyperphosphorylation and lead to the onset of Alzheimer disease." (PMID 33820886, 2021). "The GSK-3β inhibition induces an increase of the Wnt/β-catenin pathway, thus exerting a neuroprotective action against the oxidative stress and neurotoxicity induces of Aβ in the Alzheimer’s disease." (PMID 33171772, 2020). "Indeed, both GSK-3β overactivation and memory defects are observed in neurological disorders such as Alzheimer’s disease, Parkinson’s disease, major depression, bipolar disorders, and schizophrenia." (PMID 33106552, 2020). "Gsk3β is a kinase whose overactivity is attributed to Alzheimer’s disease pathogenesis." (PMID 32492972, 2020). "Recent studies have identified GSK-3β as a potential therapeutic target in Alzheimer’s disease." (PMID 33328879, 2020). "Inhibitors of GSK3β protect against Alzheimer’s disease and are therapeutic for several cancers." (PMID 33110096, 2020). "Particularly, the isoform GSK3β is related to pathologies such as Alzheimer’s disease (AD)." (PMID 32326204, 2020). "Thus, CBD, through modulation of PI3K/Akt signaling, is capable of regulating GSK3β activity and consequently improve hallmarks of Alzheimer’s disease." (PMID 33171772, 2020).